SCN9A (sodium voltage-gated channel alpha subunit 9)
Diseases named in the same sentence as SCN9A in open-access papers (continued):
Sharing a sentence is not in itself a finding about the gene and the disease.
fibromyalgia (8 papers, 2012 to 2025). A chronic disorder of unknown etiology characterized by pain, stiffness, and tenderness in the muscles of neck, shoulders, back, hips, arms, and legs. "A previous study suggested a link between the SCN9A single nucleotide polymorphism rs6754031 and the development of fibromyalgia in a group of Mexican women." (PMID 33487118, 2021). "A 61-year-old female with a history of acute facial pain, chronic pain, fibromyalgia, and constipation was found to have a gain of function SCN9A mutation by whole exome sequencing." (PMID 27525141, 2016). "This information lead us to the present investigation whose objective was to search for an association between several SCN9A sodium channels gene polymorphisms and fibromyalgia." (PMID 22348792, 2012). "The aim of this study was to search for an association between fibromyalgia and several SCN9A sodium channels gene polymorphisms." (PMID 22348792, 2012). "Notably, a study of Mexican women demonstrated that an SCN9A polymorphism significantly correlated with women diagnosed with fibromyalgia." (PMID 27525141, 2016). "The present study conducted in southern Spanish women with fibromyalgia showed that the genotype of the rs4453709 (SCN9A gene) was individually related to reduced motivation." (PMID 33924903, 2021). "For instance, the sodium voltage-gated channel alpha subunit 9 (SCN9A) gene have been recently proposed as part of the pathogenesis of fibromyalgia." (PMID 33924903, 2021). "It would be interesting to see if other patients with fibromyalgia and central sensitization syndrome have mutations in SCN9A or proteins that support Nav1.7 function, like scaffolds of anchoring proteins." (PMID 27525141, 2016).
neuroblastoma (8 papers, 2014 to 2024). Neuroblastoma (NB) is the most common solid, extracranial childhood tumor. "The lung cancer cells H460 only express SCN3A and SCN9A, whereas the neuroblastoma cells SHSY express SCN1A, SCN2A, SCN3A, and SCN9A." (PMID 31329011, 2019). "In neuroblastoma ND7 cells, a nuclear interaction between the developmentally regulated transcription factor Brn-3a and AR resulted in a complex which bound to multiple elements within the promoter region of SCN9A (Nav1.7) and upregulated channel expression." (PMID 24493753, 2014).
anhidrosis (7 papers, 2017 to 2025). Lack of sweating or the ability to sweat when provoked by the appropriate stimulus. "However, a recent case report has described individuals with SCN9A mutations presenting not only with CIP but also with anhidrosis —features more characteristic of CIPA." (PMID 40735709, 2025). "Furthermore, HSAN type IID, caused by a mutation in SCN9A, was recently reported to show anhidrosis and cognitive impairment in addition to insensitivity to pain." (PMID 38581121, 2024). "Our study identified two mutations in NTRK1 gene in Palestinian CIPA unrelated families, and a novel mutation in SCN9A gene that causes CIP without Anhidrosis." (PMID 37248554, 2023). "Most of the mutations that cause CIP without anhidrosis fall in SCN9A gene." (PMID 37248554, 2023). "But because mutations in SCN9A were not reported in our region, we did WES for the patient with CIP and without anhidrosis." (PMID 37248554, 2023).
generalized epilepsy (5 papers, 2017 to 2024). Epilepsy that is characterized by generalized seizure types and may have typical interictal and/or ictal EEG findings that accompany generalized seizure types (for example generalized spike-wave). "Pathogenic variants in the SCN9A gene have been associated with several autosomal dominant conditions, including familial febrile seizures 3B (613863) and generalized epilepsy with febrile seizures plus type 7." (PMID 38110787, 2024).
ovarian carcinoma (5 papers, 2015 to 2024). A malignant neoplasm originating from the surface ovarian epithelium. "Since lidocaine acts on sodium voltage channels, we also explored the association between SCN9A gene expression and long-term prognosis in ovarian cancer patients." (PMID 35070949, 2021). "TIPN was associated with SCN9A-rs13017637 in Japanese breast or ovarian cancer patients who received taxane." (PMID 32295642, 2020). "Our study also showed that the Nav1.7 channel encoded by the gene SCN9A may play a role in ovarian cancer cell biology: Patients with high expression of this gene showed worse survival." (PMID 35070949, 2021). "The mRNA expression analysis demonstrated that SCN9A is expressed in ovarian cancer tissues, though at slightly lower levels than in controls." (PMID 35070949, 2021). "mRNA expression of SCN9A in normal versus ovarian cancer tissue." (PMID 35070949, 2021). "For mRNA SCN9A expression analysis, we included women with all types of ovarian cancer (stages 1-4) who might have received primary debulking surgery and adjuvant chemotherapies." (PMID 35070949, 2021). "In this study, we explored whether intraoperative lidocaine reduces intraoperative opioid use and length of stay (LOS) and improves long-term survival after primary debulking surgery for ovarian cancer and explored the correlation between SCN9A expression and ovarian cancer prognosis." (PMID 35070949, 2021).
Arrhythmia (3 papers, 2015 to 2025). Any cardiac rhythm other than the normal sinus rhythm. "Similarly, alterations in SCN9A could influence NaV1.7 channel function in cardiac myocytes, potentially increasing susceptibility to BrS-related arrhythmias." (PMID 40722809, 2025).
breast carcinoma (3 papers, 2014 to 2024). "GJB2 and SCN9A have been linked to invasion and proliferation in prostate, lung, gastric, and breast cancer, as well as metastasis and worse prognosis in several cancer types." (PMID 38177502, 2024). "In addition, SCN9A-rs13017637 was significantly associated with grade 2 or higher TIPN among the 135 breast cancer patients (OR, 5.053, P = 0.0029)." (PMID 32295642, 2020). "SCN9A-rs13017637 was a significant predictor of grade 2 or higher TIPN (odds ratio (OR) = 3.463; P = 0.0050) after correction for multiple comparisons, and precision was improved when only breast cancer patients were included (OR 5.053, P = 0.0029)." (PMID 32295642, 2020).
epileptic syndromes (3 papers, 2020 to 2025). "Variants in CHD2, CACNA1A, SCN2A, SCN9A, and other genes identified in our cohort have been previously linked to epileptic syndromes." (PMID 41302954, 2025). "Mutations in CACNA1E, SCN1B, and SCN9A were previously associated with various epilepsy syndromes." (PMID 32466254, 2020). "In this study, children with CHD4 mutations presented as CAE, BECTS, and EFS+, similar as several previously reported genes associated with idiopathic epilepsy, such as GABRG2, SCN9A, and GRIN2A,45, 46 suggesting these epileptic syndromes potentially have similar etiologies." (PMID 34109749, 2021).
lung cancer (3 papers, 2019 to 2023). A malignant neoplasm involving the lung. "On the other hand, a study performed in NSCLC reported that the functional expression of SCN9A (Nav1.7) is controlled by EGF/EGFR signaling through the ERK1/2 pathway, which in turn promotes the invasion of H460 lung cancer cells." (PMID 37408210, 2023).
autism (2 papers, 2020 to 2021). Persistent deficits in social interaction and communication and interaction as well as a markedly restricted repertoire of activity and interest as well as repetitive patterns of behavior. "Hence, they concluded that rare mutations of SCN9A were involved in the etiology of autism in some families." (PMID 34947986, 2021).
autism spectrum disorder (2 papers, 2018 to 2021). A spectrum of developmental disorders that includes autism, and Asperger syndrome. "Further studies showed that rare mutations of SCN9A were associated with seizure and autism spectrum disorders." (PMID 34947986, 2021).
autonomic dysfunction (2 papers, 2023 to 2025). "Carriers of SCN9A mutations are frequently affected by autonomic dysfunction." (PMID 36979316, 2023).
Cognitive impairment (2 papers, 2017 to 2024). Abnormal cognition is characterized by deficits in thinking, reasoning, or remembering. "Transcripts predictive of cognitive performance under high stress included genes that are associated with a high occurrence of Alzheimer's and cognitive impairments (e.g., Ncl, Eno1, Scn9a, Slc19a3, Ncstn, Fos, Eif4h, Copa, etc.)." (PMID 28912681, 2017).
endometriosis (2 papers, 2014 to 2021). The growth of functional endometrial tissue in anatomic sites outside the uterine body. "We believe this is the first study to detect differences in the expression of mRNAs encoded by the ion channels TRPA1, P2RX3, SCN9A, and SCN11A in the peritoneum and lesions of women suffering from CPP, some of whom had endometriosis." (PMID 25029427, 2014). "In a study of the peritoneum of women with endometriosis, TRPV1 and SCN9A (Nav1.7) mRNA expression was enhanced, although other recent studies demonstrated that Nav1.7, despite being related to acute and somatic pain, is not required for visceral pain signaling." (PMID 34357968, 2021). "TRPV1, SCN9A, and TAC1 were elevated in endometriosis lesions (P < .05)." (PMID 25029427, 2014). "SCN9A (Nav1.7) was elevated in lesions from women with endometriosis (P < .05), whereas SCN11A was significantly higher in the peritoneum of women with CPP and endometriosis compared with the peritoneum of women with CPP alone (P < .001)." (PMID 25029427, 2014). "In summary, the results of this study indicate that therapies targeting P2RX3 may be useful in treating CPP in women with a diverse range of painful etiologies, whereas women with active endometriosis could benefit from treatments targeting TRPV1, TRPA1, SCN9A, or SCN11A." (PMID 25029427, 2014).
interstitial cystitis (2 papers, 2013 to 2016). A rare chronic debilitating urogenital disease characterized by urinary frequency, urgency, and pelvic pain. "For example, the high-pain variant of the SCN9A gene was found to be present in 12% of normal controls and 40% of patients with interstitial cystitis—not 100% of interstitial cystitis patients." (PMID 27790160, 2016).
iron overload (2 papers, 2014 to 2020). "Thanks to exomic capture, we reorientated initial diagnosis for P35 (probable myeloproliferative syndrome) and explained a part of the phenotype in P24 (osteonecrosis and TRPV4), P26 (HAMP and iron overload) and P35 (painful crisis and SCN9A)." (PMID 32641076, 2020).
Ataxia (1 paper, 2020). Ataxia refers to impaired coordination of voluntary muscle movement. "Additional work to establish the functional effects of our identified mutation in SCN9A and to definitively link this variant to the ataxia phenotype is still required." (PMID 32466254, 2020). "Three likely pathogenic variants in these genes were identified in Case-21 (CACNA1E p.Ile614Val), Case-25 (SCN1B p.Cys121Trp), and Case-31 (SCN9A p.Tyr1217Ter), with very late onset of ataxia at the age of 60, 59, and 56, respectively." (PMID 32466254, 2020).
brain cancer (1 paper, 2024). A primary or metastatic malignant neoplasm affecting the brain. "Notably, GJB2 and SCN9A show prominent expression in neoplastic cells and are associated with poor prognosis in glioblastoma, the most common and aggressive brain cancer." (PMID 38177502, 2024).
complication (1 paper, 2023). Any disease or disorder that occurs during the course of, or because of, another disease, treatment, or procedure. "In their series, patients with SCN9A variants had an earlier age of onset, a greater severity of pain, poorer responses to analgesic management, and more frequent skin complications compared to those without pathogenic SCN9A variants." (PMID 37628281, 2023).
congenital megacolon (1 paper, 2025). "TGex analysis (LifeMap Sciences, USA) prioritized 9 candidate variants across 7 genes (MED13, POGZ, SETBP1, SCN9A, SCO1, APTX, TIE1) associated with phenotypes including congenital megacolon, intellectual disability, motor delay, and developmental delays." (PMID 41195223, 2025).
corneal opacities (1 paper, 2022). "We found that patients with PRDM12 variant had more severe manifestations of ocular surface disease, with more prevalent corneal opacities and worse visual acuity, compared to patients with SCN9A variant." (PMID 36111846, 2022).
COVID-19 (1 paper, 2024). A disease caused by infection with severe acute respiratory syndrome coronavirus 2. "To verify whether changes in SCN9A expression in ROEB observed in COVID-19–infected mice and hamsters were also observed in humans, we tested the NaV1.7 expression in the OSNs of cadavers." (PMID 38960711, 2024).
cryptorchidism (1 paper, 2023). The failure of one or both testes of a male fetus to descend from the abdomen into the scrotum during the late part of pregnancy. "Of the six SCN9A variant patients, four were diagnosed with GEFS+, one with CFS, one with non-specific EE, and one patient had comorbid cryptorchidism." (PMID 38174099, 2023).
developmental and epileptic encephalopathies (1 paper, 2025). "Mutations in SCN1A, SCN2A, SCN3A, and SCN9A genes are known to cause autosomal dominant developmental and epileptic encephalopathies, with haploinsufficiency as a primary mechanism." (PMID 40894531, 2025).
glioma (1 paper, 2024). A benign or malignant brain and spinal cord tumor that arises from glial cells (astrocytes, oligodendrocytes, ependymal cells). "Besides GBM, GJB2, and SCN9A expression associated with poor prognosis in low-grade glioma, kidney, and uterine cancer, lending further confidence to these genes." (PMID 38177502, 2024). "We validated the survival associations of GJB2 and SCN9A expression in two independent GBM cohorts, including 136 samples from the Glioma Longitudinal Analysis (GLASS) and 55 samples from an earlier microarray dataset." (PMID 38177502, 2024).
Hypertension (1 paper, 2024). The presence of chronic increased pressure in the systemic arterial system. "With regard to genes encoding Na+ channels, Scn9a was persistently upregulated in the RVLM with the exception of 12 wk, whereas Scn8a and Scn1a appeared to show upregulation in the NTS around the onset of hypertension at 10 and 12 wk." (PMID 38145287, 2024).
myeloma (1 paper, 2022). "In agreement with the gene model, compared with bortezomib-sensitive myeloma cell lines (negative control), there was an increase in mRNA expression of SCN9A, RGS7, NTF3, HSPB8, and ZBED1 and a decrease in CCND1, COBLL1, EGR1, OCLN, and ZBED1 mRNA expression of bortezomib-resistant cell lines." (PMID 36467498, 2022).
cancer (29 papers, 2008 to 2025). A tumor composed of atypical neoplastic, often pleomorphic cells that invade other tissues. "GJB2 and SCN9A are implicated in monogenic diseases with emerging implications in cancer." (PMID 38177502, 2024). "In this study we investigated whether SCN9A genetic variants were associated with risk of neurotoxicity in patients diagnosed of cancer on treatment with oxaliplatin." (PMID 28103821, 2017). "Although evidence suggests that genetic variants in SCN9A are associated with distinct pain perception in oxaliplatin-treated cancer patients, the role of Nav1.7 mediating oxaliplatin-induced pain remains controversial." (PMID 40283194, 2025). "As previously indicated, the three main NaVα-encoding genes found to be upregulated in cancers are SCN5A, SCN8A, and SCN9A, which encode NaV1.5, NaV1.6, and NaV1.7, respectively." (PMID 33817575, 2021). "In particular, the GSE34053 dataset analyzed cancer-associated fibroblasts (CAF, tumor stromal cells) and CD133+ cells (tumor epithelial cells); while CD133+ cells expressed higher levels of KCNAB2 and KCNMB4, CAF cells (stroma) overexpressed SCN9A and KCNJ8 subunit channels." (PMID 33802791, 2021). "Just as a massiveresearch attack on cancer genetics in the 1980s is now paying dividends in terms ofdrug treatment, so the genetic description of key signalling molecules and mediatorsin the pain system has provided many new targets (e.g., P2RX7,SCN9A) for analgesic drugs that are under development." (PMID 18654615, 2008).
small fibre neuropathy (21 papers, 2013 to 2025). "SCN9A rs6746030 was associated with protection for severe oxaliplatin-induced peripheral neuropathy." (PMID 28103821, 2017). "This NAT is therefore a potentially interesting candidate gene for IEM, PEPD and small fibre neuropathy patients that lack pathogenic mutations in SCN9A." (PMID 26035178, 2015). "A further series of gain of function variants in SCN9a have been associated with the development of small fibre neuropathy." (PMID 23500200, 2013). "Among various predisposing conditions, mutations in the SCN9A and SCN10A genes are often related to the development of small-fibre neuropathy." (PMID 36558965, 2022). "In humans, loss-of-function mutations in SCN9A, the gene encoding NaV1.7, leads to congenital insensitivity to pain, while several gain-of-function mutations in SCN9A and SCN10A (the gene encoding NaV1.8) are associated with painful peripheral neuropathies." (PMID 32092883, 2020). "Gene alterations, such as GSTP1 and GSTM1, glutathione-S-transferase genes and voltage-gated sodium channel genes SCN4A, SCN9A and SCN10A, together with pre-existing peripheral neuropathy have been demonstrated to be the principal risk factors for OIPN onset." (PMID 33671327, 2021).
tumor (14 papers, 2015 to 2025). "The SCN9A gene encodes Nav1.7, a voltage-gated sodium channel and is recognized as an oncogene and has been implicated in tumor initiation, progression, and drug resistance." (PMID 41163355, 2025). "Silencing of NaV1.7 (sh-SCN9A) in mouse models using BGC-823/sh-SCN9A cells showed a depletion of tumor growth." (PMID 39045054, 2024). "An in vivo study showed the silencing of NaV1.7 expression (sh-SCN9A) reduced the tumor sizes of mice models." (PMID 39045054, 2024). "Kaplan-Meier curves also indicated significantly shorter progression-free survival and OS among women with tumours expressing higher than the median SCN9A mRNA level." (PMID 35070949, 2021). "Analogously, SCN9A and SCNN1B down-regulation was highly associated with tumor epithelial cell-enriched fractions." (PMID 33802791, 2021). "We characterized GJB2 and SCN9A expression in GBM tumor regions and subtypes." (PMID 38177502, 2024). "Thus, GJB2 and SCN9A are downregulated in anatomical regions with fewer tumor cells, while GJB2 is upregulated in highly proliferative and motile regions of GBMs." (PMID 38177502, 2024). "In GBM, we focused on two IP genes, GJB2 and SCN9A, and demonstrated their roles in promoting GBM aggression using patient-derived tumor cells and xenograft models." (PMID 38177502, 2024). "The inhibition of NaV1.7 either by small molecules at low μM concentrations or Sh-SCN9A showed 40%–60% reduction in cell invasion/migration in vitro and a reduction in tumor growth rate in vivo." (PMID 39045054, 2024).
neurological disorders (6 papers, 2017 to 2024). "Moreover, we identified 3 upregulated [ENO3, LPIN1 and SCN9A] and 3 downregulated [ATL3, CPT1C, and SGCB] RNAs whose genes have been implicated in neurological disorders." (PMID 34907471, 2022).
genetic diseases (5 papers, 2010 to 2025). "Hence, congenital SCN9A loss-of-function mutations, such as congenital insensivity to pain and type IID of hereditary sensory and autonomic neuropathy, can induce genetic diseases with a complete absence of pain." (PMID 30233376, 2018).
infection (3 papers, 2014 to 2024). The state of being infected such as from the introduction of a foreign agent such as serum, vaccine, antigenic substance or organism. "In SARS-CoV-2–infected hamsters, we observed a 3-fold drop in expression of the SCN9A gene transcripts in OSNs at 3 d after infection and full recovery of expression at 10 d after infection with bulk RNA sequencing analysis (P < 0.001)." (PMID 38960711, 2024).